VTRNA2-2P (vault RNA 2-2, pseudogene)
Gene: Miscellaneous RNA gene on chromosome 2 (65,555,432 to 65,555,534, reverse strand). Ensembl gene ENSG00000251900.
Homologues: Orthologues: chimpanzee Vault (99% identical), macaque Vault (89% identical), rat Vault (57% identical), mouse Vaultrc-ps1 (56% identical), mouse Vaultrc5 (56% identical), tropical clawed frog Vault (56% identical), tropical clawed frog Vault (54% identical), tropical clawed frog Vault (53% identical), tropical clawed frog Vault (52% identical), tropical clawed frog Vault (48% identical). Paralogues in human: Vault (72% identical), Vault (68% identical), VTRNA1-1 (54% identical), VTRNA3-1P (50% identical), VTRNA1-2 (50% identical), Vault (50% identical), VTRNA1-3 (48% identical).